TROAP (trophinin associated protein)
Diseases named in the same sentence as TROAP in open-access papers (continued):
Sharing a sentence is not in itself a finding about the gene and the disease.
tumor (continued). "Moreover, the Pearson correlation analysis showed that the expression of circMBOAT2 had a negative correlation with miR-519d-3p and a positive correlation with TROAP in CRC tumor tissues, as detected by qRT-PCR." (PMID 32796815, 2020). "On the other hand, TROAP downregulation suppressed tumor cell proliferation." (PMID 31198787, 2019). "Knockdown of FAM64A or TROAP inhibited the growth of cancer cells, suggesting that these genes may promote tumor development and are worthy of further validations." (PMID 28489584, 2017). "We then considered whether interfering with TROAP could affect tumor growth in vivo." (PMID 37298609, 2023). "Therefore, Tumor progression may be facilitated by TROAP activating the PI3K/Akt/GSK3β signaling pathway." (PMID 36419876, 2022). "Therefore, for tumor patients with high TROAP expression, blocking TROAP might be a promising therapeutic modality." (PMID 36419876, 2022). "Moreover, Correlation analysis showed a positive correlation between immune checkpoint genes and TROAP expression in the majority of tumor types, manifesting that TROAP may be involved in immune escape." (PMID 36419876, 2022). "Finally, we confirmed that blocking DYRK1 with AZ191 could inhibit tumor growth for TROAP-overexpressed HCC cells in mouse." (PMID 33500384, 2021). "Importantly, an inhibitor of DYRK1A/B AZ191 could inhibit tumor growth in mice for HCC cells with high level of TROAP." (PMID 33500384, 2021). "TIMER tool further revealed expression of the 5 signature genes (ZNF695, CENPA, TROAP, BIRC5 and KIF20A) was strongly and positively correlated with high tumor purity but negatively influenced the infiltration of CD8+ T cells and macrophages." (PMID 33995639, 2021). "CO-IP and post-mass spectrometry bioinformatics analyses revealed that TROAP may combine with signal transducer and activator of transcription 3 (STAT3) to achieve tumor progression in KIRC; this was verified by functional recovery experiments." (PMID 37298609, 2023). "In order to investigate the effects of TROAP expression on tumor growth in vivo, A375 cells transfected with TROAP or negative control were injected subcutaneously into nude mice xenograft model respectively." (PMID 37127623, 2023). "The noncancerous MCF-10A cells showed lower levels of both TROAP mRNA and protein compared to the tumor cell lines." (PMID 31198787, 2019). "We also detected TROAP protein expression levels in 10 pairs of tumor and noncancerous tissues and found them to be upregulated in all tumor tissues compared to matched noncancerous tissues." (PMID 31198787, 2019). "The results demonstrated that TROAP mRNA expression was significantly higher in BC tumor tissues than in matched noncancerous adjacent tissues." (PMID 31198787, 2019). "Our study analyzed the TCGA dataset and found that TROAP mRNA expression was significantly increased in BC tumor tissues (N, noncancerous; T, tumor; P<0.001) and in all molecular subtypes of BC (basal-like, HER2 overexpressed, luminal A and luminal B; P<0.001)." (PMID 31198787, 2019). "Mechanism analysis revealed that TROAP silence could significantly downregulate the level of downstream target genes of PI3K/Akt/GSK-3β signaling, confirming that TROAP-induced malignant biological behavior and tumor progression via PI3K/Akt/GSK-3 signaling pathway." (PMID 36419876, 2022). "This led to the selection of seven antigens found to be overexpressed in both mouse MM tumor lines under investigation and that were nearly absent in all other mouse normal tissues: KIF20A, KIF2C, MMP9, MNDA, OLFML2B, TROAP, and ULBP1." (PMID 31428586, 2019). "Since most pan-cancer genes have no explicit functions in tumor development, we validated the functions of two pan-cancer genes, FAM64A and TROAP, in tumor progression." (PMID 28489584, 2017).
cancer (11 papers, 2017 to 2023). A tumor composed of atypical neoplastic, often pleomorphic cells that invade other tissues. "Mechanistically, the depletion of TROAP was found to cause cell cycle arrest and inhibition of multiple cancer growth-promoting pathways." (PMID 37900285, 2023). "The TROAP gene was altered, accounting for only 1.5% across 10,967 samples, and the most frequent alteration was a mutation, which occurred in 17 cancer types." (PMID 36419876, 2022). "TROAP (Trophinin-associated protein, also known as TASTIN) is found to participate in the proliferation, invasion, and migration of many cancers." (PMID 35251990, 2022). "Additionally, mutation of the TROAP gene was intimately correlated with TROAP transcriptional expression in pan-cancer." (PMID 36419876, 2022). "Then, TROAP is significantly disparately expressed in diverse immune and molecular subtypes of most tumors and may be a hopefully pan-cancer diagnostic biomarker involved in immune regulation." (PMID 36419876, 2022). "Therefore, we further examined the association between TROAP levels and infiltrating levels of 22 immune cell types in pan-cancer derived from CIBERSORT, showing that TROAP expression was significantly related to various immune cell subtypes." (PMID 36419876, 2022). "Furthermore, we found a significant association between TROAP expression and molecular subtypes in various cancers." (PMID 36419876, 2022). "Trophinin-associated protein (TROAP) is a cytoplasmic protein required for microtubular cytoskeleton regulation and spindle assembly, and its expression plays a critical role in the initiation and progression of various types of cancer." (PMID 31198787, 2019). "The rest 25 genes including CENPI, COMP and TROAP may be novel cancer-associated genes that are worthy of validation in further studies." (PMID 28489584, 2017). "The results display that the enhanced expression of TROAP is associated with attenuated immune cell infiltration, decreased stromal and immune activation, and diminished activity of the cancer immune cycle, which may be accounting for the poor prognosis of STS with TROAP overexpression." (PMID 37731946, 2023). "TROAP expression in cancer tissues of patients with different T and pathological stages of KIRC was significantly different, suggesting a correlation." (PMID 37298609, 2023). "In the TCGA database, the expression of TROAP in cancer tissue samples was significantly higher than that in the adjacent tissues." (PMID 37298609, 2023). "For instance, in KIRC, miR-532-3p reduced cancer cell viability, migration, and invasion by targeting TROAP." (PMID 37298609, 2023). "Lastly, TROAP can be used as the target of some microRNAs to inhibit the proliferative activity of cancer cells." (PMID 37298609, 2023). "In the last years, accumulating research has demonstrated that TROAP acts as a significant factor in the development and progression of various cancers." (PMID 37731946, 2023). "Collectively, our comprehensive pan-cancer analysis showed the characteristics of TROAP in multiple ways, including expression pattern, survival prognosis, genetic mutation, TMB, MSI, MATH, immune TME, and drug resistance." (PMID 36419876, 2022). "Correlation analysis of TROAP expression with ESTIMATE scores in pan-cancers according the RNA sequencing data from TCGA database." (PMID 36419876, 2022). "The TISIDB database revealed significant correlations between TROAP expression levels and immune subtypes in 20 cancers." (PMID 36419876, 2022). "The forest plots showed that high TROAP expression predicted poor DSS in 15 cancers and poor DFI in 18 cancers." (PMID 36419876, 2022). "In this study, an extensive examination of the role of TROAP in a variety of cancers was undertaken with the aim of demonstrating a comprehensive workflow for pan-cancer analysis." (PMID 36419876, 2022).
cancer (continued). "Then, the GSCA database was used to indicate a substantial positive connection between the copy number variation (CNV) of the TROAP gene and its mRNA expression levels in 26 cancers." (PMID 36419876, 2022). "On the contrary, the biological role of TROAP in the progression of cancers and its correlation with prognosis, TME, and prediction of drug sensitivity is still unclear in the systematic analyses." (PMID 36419876, 2022). "TMB and MSI of cancer are affected by TROAP expression, which affects treatment response to immune checkpoint suppression." (PMID 36419876, 2022). "We will further explore the specific mechanisms by which TROAP is involved in chemotherapy resistance in different cancers, which will be important in guiding personalized clinical dosing decisions." (PMID 36419876, 2022). "The results showed a strong positive correlation between TROAP and most gene markers relevant to RNA modification in various cancers." (PMID 36419876, 2022). "Mounting evidence demonstrates the vital role of TROAP in regulating the proliferation and migration of cells, but it is unclear how it contributes to cancer progression." (PMID 36419876, 2022). "TROAP expression was significantly upregulated in most cancer types, which is consistent with our validated experimental results in HCC and CRC cells, and immunohistochemistry results." (PMID 36419876, 2022). "The main functions of TROAP were revealed to promote the proliferation and metastasis of cancer cells." (PMID 33500384, 2021). "These superficial studies revealed that TROAP expression was upregulated in cancer tissues, predicting the worse outcome of cancer patients." (PMID 33500384, 2021). "By analyzing TCGA database, we characterized that TROAP was significantly high expressed in 23 kinds of cancers, including HCC." (PMID 33500384, 2021). "The GSE6919 dataset showed similar results with TROAP mRNA being overexpressed in cancer tissues, but the overexpression was especially high in tissues with metastasis." (PMID 33692939, 2020). "Moreover, TROAP may be associated with the invasion and migration of various cancers." (PMID 31198787, 2019). "Recently, TROAP was found to participate in the proliferation, invasion, and migration of many cancers." (PMID 31198787, 2019). "In conclusion, the present study confirmed that TROAP contributes to BC cancer proliferation, invasion, and metastasis." (PMID 31198787, 2019). "The high expressions of TROAP could promote the proliferation and metastasis of cancer cells, leading to a poor prognosis." (PMID 37298609, 2023). "TOP2A, CENPF, TROAP, CDC20, CDCA5, and UBE2C are all reported to be associated with cancer." (PMID 36932399, 2023). "However, high levels of TROAP have been reported in several cancer types, including serous ovarian carcinoma, suggesting its utility as a marker for cancer progression and prognosis." (PMID 37900285, 2023). "Based on the TCGA database, we preliminary analyzed the expression of TROAP in pan‐cancer." (PMID 37731946, 2023). "The role of TROAP in cancer has been extensively studied and could be different depending on the type and stage of the disease." (PMID 37900285, 2023). "These experiments demonstrated that TROAP is an oncogene that could aggravate the malignancy of cancer cells." (PMID 37298609, 2023). "TROAP mRNA levels were remarkably higher in 33 human cancers than in adjacent tissues." (PMID 36419876, 2022). "As TROAP is abnormally expressed across multiple cancers and predicts worse outcomes in cancer patients, it might be an effective cancer therapy target." (PMID 36419876, 2022). "Furthermore, TROAP participates in the invasion and migration of multiple cancers, for instance, lung, liver, and breast cancer." (PMID 36419876, 2022). "Therefore, we evaluated cancer samples and adjacent normal tissues for TROAP expression differences and their correlation with prognosis in pan-cancer according to bioinformatic analyses." (PMID 36419876, 2022).
cancer (continued). "TROAP was expressed at low levels in the C3 (inflammatory) type in most of the 20 cancers." (PMID 36419876, 2022). "Our analysis found a positive correlation between TROAP and Treg cells in 13 cancers." (PMID 36419876, 2022). "TROAP promotes oncogenesis and cancer progression, according to these results." (PMID 36419876, 2022). "Moreover, TROAP expression was apparently associated with poor prognosis and DFS in various cancers." (PMID 36419876, 2022). "Furthermore, TROAP expression was significantly related to MSI in 14 cancers, NEOs in six cancers, and MATH in 16 cancers." (PMID 36419876, 2022). "We performed follow-up experiments to determine whether TROAP influences cancer cell biological behavior." (PMID 36419876, 2022). "The upregulation of TROAP expression in cancer tissues and immune cells may be involved in immune regulation." (PMID 36419876, 2022). "In cancer patients, levels of TROAP methylation could be used as a biomarker of prognosis based on TROAP expression and DNA methylation." (PMID 36419876, 2022). "Therefore, this may indicate that the TROAP expression level affects the MATH of cancers and the patient’s OS." (PMID 36419876, 2022). "Hence, TROAP is a promising biomarker and therapeutic target for predicting cancer outcomes." (PMID 36419876, 2022). "Therefore, tumorigenesis and cancer progression may be influenced by TROAP genomic alteration and differential expression in cancer tissues." (PMID 36419876, 2022). "Additionally, aberrant TROAP expression occurs in different human cancers." (PMID 35251990, 2022). "We also found that FAM64A and TROAP could predict overall survival in multiple other cancer types." (PMID 28489584, 2017). "Overall, we concluded that TROAP was highly expressed in KIRC and promoted cancer cell proliferation, invasion, and metastasis." (PMID 37298609, 2023). "Our study confirmed that TROAP was involved in the proliferation and invasion of KIRC and was combined with STAT3 to exert a synergistic effect in promoting cancer, which is expected to be a new therapeutic target for KIRC." (PMID 37298609, 2023). "The online portals of GEPIA2, Cancer Cell Line Encyclopedia, UALCAN, Human Protein Atlas, and PrognoScan were used to analyze TROAP expression in various tumors and further evaluate its correlation with prognosis." (PMID 36419876, 2022). "As a result of these results, TROAP plays a crucial role in regulating the expression and function of gene markers related to TME in cancers." (PMID 36419876, 2022). "Knockdown of two of these genes, FAM64A and TROAP, in MDA-MB-231 cell line inhibited cancer cell growth." (PMID 28489584, 2017). "A negative relationship exists between the methylation of the TROAP gene and its mRNA levels in most cancers." (PMID 36419876, 2022). "The estimated score showed strong positive correlations with TROAP expression in six cancers and negative correlations in 23 cancers." (PMID 36419876, 2022). "Most human cancer types also showed negative correlations between TROAP and immune, stromal, and ESTIMATE scores of the TME, indicating that TROAP plays different immune regulatory roles in various cancer types." (PMID 36419876, 2022). "Collectively, these findings indicated a significant correlation between TROAP expression and malignant phenotype, functional mechanism, survival possibility, TME, therapeutic potential, and prediction of drug sensitivity in various cancers." (PMID 36419876, 2022). "Although TROAP has been recognized as an unfavorable factor in several cancers, the molecular function and precise mechanism of TROAP in tumorigenesis and proliferation of many cancers have yet to be elucidated, and no research has focused on its impact on pan-cancer." (PMID 36419876, 2022).
infection (1 paper, 2020). The state of being infected such as from the introduction of a foreign agent such as serum, vaccine, antigenic substance or organism. "In DU145 and PC3 cells, TROAP knockdown significantly inhibited cell proliferation on the 3rd, 4th and 5th days after infection." (PMID 33692939, 2020).
TROAP also shares sentences with these, for which no sentence is quoted: adrenocortical carcinoma (1 paper); anaplastic oligodendroglioma (1); asthma (1); CNS) tumors (1); lung squamous cell carcinoma (1); mesothelioma (1); microcephaly (1); oligodendroglioma (1); pilocytic astrocytoma (1); pleomorphic xanthoastrocytoma (1); skin cutaneous melanoma (1); small cell lung carcinoma (1); thyroid carcinoma (1); type 1 diabetes mellitus (1); uterine corpus endometrial carcinoma (1).